CRP (C-reactive protein)
Diseases named in the same sentence as CRP in open-access papers (continued):
Sharing a sentence is not in itself a finding about the gene and the disease.
Cachexia (continued). "In agreement with cachexia having been characterized by chronic inflammation, cachectic patients in our study presented with significantly higher CRP serum levels than in the non-cachectic control group (median 2 vs 0.6 mg/dL, p < 0.01)." (PMID 34182958, 2021). "The median CRP concentration in the group with cachexia but without inflammation was 4.0 vs. 22.0 in the group with cachexia with inflammation." (PMID 34830921, 2021). "Our data support this notion since the higher CRP levels of the ‘no cachexia’ group did not translate into increases in other inflammatory molecules known to be elevated in cachexia, such as IL-6, or the complement factors C3a, TCC, and C1q." (PMID 34830921, 2021). "Our survey showed for both MNA-SF and NRS-2002 assessed patients, there was a statistically significant correlation between cachexia and CRP (P < 0.01), while the correlation between cachexia and SA was not statistically significant." (PMID 31388102, 2020). "There was a small increase in CRP levels at 48 weeks in patients with follow-up cachexia (median change: + 0.280 mg/dL) and in patients without (median change + 0.580 mg/dL), which was significantly different (P = 0.044)." (PMID 32103356, 2020). "Our usage of CRP in the criteria for “laboratory cachexia” can be considered problematic as CRP is not specific for systemic inflammation." (PMID 29534089, 2018). "Multivariately, high levels of TNF-α (but not CRP, IL-1ß or IL-6) significantly predicted loss of FFMI, however only in patients with established cachexia at entry." (PMID 22708547, 2012). "This suggests that cachexia may be driven by chronic low-grade inflammation not reflected by standard CRP thresholds, underscoring the need for broader biomarker panels in future studies." (PMID 40906320, 2025). "In addition to low albumin and high CRP, low AKPS is a plausible additional surrogate of cachexia, and this relationship to noroxycodone could also be studied in future." (PMID 39628313, 2024). "Furthermore, intramyocellular lipid content increased with both local inflammation (IL‐6) and systemic inflammation (CRP) in PDAC patients with or without cachexia." (PMID 38725139, 2024). "Second, some of the well-accepted markers as systemic inflammation (e.g., CRP) are not consistently increased in cancer cachexia populations so, in a similar way, it may result in differences in the mouse models used for this study." (PMID 37629186, 2023). "Regarding biochemistry and haematology, patients with cachexia hadsignificantly increased c-reactive protein levels (average of 30.7 vs 15.3 mg/Lin the not cachectic group), and significantly decreased albumin (37.9 vs 40.2)and red blood cell count (3.8 vs 4.2)." (PMID 35729767, 2022). "Finally, it is important to note that the ‘no cachexia group’ had elevated systemic CRP levels, indicating inflammation." (PMID 34830921, 2021). "In the present study, a diagnosis of cachexia was simply determined to meet BMI < 20 kg/m2, FFMI (≤17.4 kg/m2 for males and ≤15 kg/m2 for females), and at least two additional biochemical criteria (Hb level < 12 g/dL, CRP level < 5 mg/dL, Alb level < 3.2 g/dL)." (PMID 32781732, 2020). "Possibly, other factors, not studied, related to BMI and cachexia like CRP, skinfold and skin condition might also influence absorption." (PMID 29883454, 2018). "Though we saw a significant difference in CRP-value between cachexia and non-cachectic patients." (PMID 28193264, 2017). "When we subdivided patients according to their nutritional status, cachectic patients as a whole group had a mean CRP value of 34.18 mg/l (+/−51.9) and patients without cachexia had a mean value of CRP 17.57 mg/l (+/−27.5) which was also significantly different (p = 0.021)." (PMID 23294910, 2013). "Thus, it would seem reasonable that higher systemic levels of CRP, TNF-α, IL-1ß, and IL-6 could be contributing factors to cachexia also in COPD patients." (PMID 22708547, 2012).
Cachexia (continued). "However, since we first stratified the patients according to their cachexia status before subdividing the cachexia group according to CRP level, we consider that CRP elevations in the ‘no cachexia’ group were not related to the metabolic and inflammatory alterations that come with cachexia." (PMID 34830921, 2021). "Moreover, increased level of inflammatory markers was noted in cachectic patients compared to women without symptoms of cachexia (median CRP level: 10.95 mg/L (1.96–26.20) and 3.10 mg/L (1.45–4.95); p = 0.005; median TNF-α level: 4.48 pg/mL (3.49–5.13) and 3.29 pg/mL (3.07–4.91); p = 0.032)." (PMID 32260434, 2020). "Unlike in humans, C Reactive Protein (CRP) is not an acute phase protein in mice and was not elevated in cachexia." (PMID 21799891, 2011). "Several clinical studies have reported that the increase of C-reactive protein (CRP), a liver-derived positive acute phase protein (APP), and a decrease of albumin, a negative APP, correlates with severity of cachexia and negatively with prognoses of cancer patients." (PMID 37803016, 2023).
co-infection (147 papers, 2010 to 2026). "B. pertussis and rhinovirus co-infection was associated with a decreased SpO2 level (<92%) and increased CRP and Ferritin levels." (PMID 41157187, 2025). "B. pertussis and rhinovirus co-infections were associated with a significant increase in CRP and ferritin levels (p = 0.014, p = 0.035), with mean values of 1.3, respectively, 253.3 vs. 0.52 and 94.75 in single B. pertussis infections." (PMID 41157187, 2025). "After adjusting for maternal HIV viral load, CD4 count and CMV co-infection, the risk of infant mortality doubled for each log rise in maternal CRP (aHR 2.09; 95% CI 1.33, 3.27)." (PMID 38632279, 2024). "We were able to show that the elevation of CRP is indeed a specific parameter of the underlying coinfection." (PMID 38398352, 2024). "Co-infections were associated with higher VL, CRP, and ferritin, but decreased iron levels at baseline." (PMID 38725704, 2024). "HSV, CMV, and EBV coinfections were associated with the highest CRP level (63.67 ± 39.96, 48.35 ± 46.58, and 23.76 ± 36.55, respectively)." (PMID 39014398, 2024). "Six months after initiating ART, the presence of co-infections was associated with significantly higher levels of CRP (5.2 [3.5–12.6] vs 3.6 [2.6–7], P = 0.019) and ferritin (136 vs 94.5, P = 0.019) than the absence of co-infections." (PMID 38725704, 2024). "What's more, joint the serum prealbumin and CRP to establish a logistic regression equation has a better diagnostic significance for Omicron and Flu A/B co‐infection (Omicron vs. co‐infection: AUC = 0.934; Flu A/B vs. co‐infection: AUC = 0.887)." (PMID 38270315, 2024). "Age ≥ 65 years and number of comorbidities were risk factors for primary co-infection in univariate analysis, and patients with co-infections had significantly higher levels of CRP and PCT." (PMID 35420370, 2022). "When looking at the association between co-infections and clinical severity of illness, the CRP (z = -2.69, p = 0.007) and initial heart rate (z = -2.54, p = 0.01) were significantly higher in co-infections." (PMID 32059033, 2020). "In this large and concise study on bacterial co-infections in children with bronchiolitis we have found that bacterial infections are common, associated with prolonged ventilation and a raised CRP." (PMID 31694565, 2019). "Bacterial–viral coinfection has been associated with altered levels of innate immune factors (e.g., CRP and IP10) and a more severe clinical course." (PMID 30625278, 2019). "A high CRP was associated with bacterial co-infection in a multivariate analysis including antibiotic use prior to PICU admission (p = 0.001)." (PMID 31694565, 2019). "Our results confirm that IL-6 and CRP are strongly associated with paradoxical IRIS in the context of HIV/TB co-infection, even after adjustment for other risk factors." (PMID 23691062, 2013). "Increased C - reactive protein (CRP), especially > 50 mg/L, was significantly associated with MD co-infections (p <0.001) relative to dengue alone." (PMID 22549018, 2012). "A CURB-65 score >1 and CRP levels proved to be useful tools to identify patients at higher risk for pneumococcal co-infection for whom physicians should adopt additional diagnostic and therapeutic measures." (PMID 21801627, 2011). "CRP was associated with bacterial co-infection and may be used to identify children at increased risk." (PMID 31694565, 2019). "Co-infection increases significantly and may be associated with elevated C-reactive protein (CRP), procalcitonin (PCT), and Interleukin-6 (IL-6)." (PMID 26744628, 2016). "In contrast, Tb+ fish (subsequent co-infection with M. cerebralis) exhibited a highly potent innate immune response, including substantial upregulation of CRP and C3, activation of IL-1 signaling, and enhanced humoral immunity." (PMID 40943072, 2025). "In the univariable analysis, age, disease course, dyspnea, RPILD, AST, ESR, CRP, CD4+T cells, CD8+T cells, co-infection and treatments showed significant association with death(all p<0.05)." (PMID 41333459, 2025).
co-infection (continued). "Nevertheless, in our research, we observed that B. pertussis and HRV co-infections were correlated with decreased SpO2 (<92%) and increased inflammatory markers (CRP and ferritin)." (PMID 41157187, 2025). "We observed significant differences in mean values of the duration of HIV infection, the presence of HCV coinfection, and serum concentrations of CRP, PCT, total cholesterol, triglycerides, and VCAM-1 among patients who lived and patients who died." (PMID 40006998, 2025). "Our study revealed that patients with co-infection exhibited elevated inflammatory markers (CRP, SAA)." (PMID 40797503, 2025). "Whereas the serum CRP and prealbumin were significantly changed in co‐infection group compared with Omicron or Flu A/B mono‐infection group." (PMID 38270315, 2024). "The present study reported diminished lymphocyte count and higher levels of C-reactive protein, transaminases, and D-dimer in the co-infection group." (PMID 38793006, 2024). "The surrogate marker of putative bacterial co-infection, CRP, was elevated in both cases and controls and was significantly higher in cases." (PMID 39506794, 2024). "The results indicated that prealbumin was more efficient than CRP in identifying co‐infection from Omicron or Flu A/B mono‐infection." (PMID 38270315, 2024). "After 6 months of ART rates of virologic suppression were very high and similar in both groups, however, markers of inflammation (CRP and ferritin) remained significantly higher in those with co-infections." (PMID 38725704, 2024). "Ferritin and CRP decreased on dolutegravir-based ART but remained higher in people with co-infections despite similar rates of virologic suppression." (PMID 38725704, 2024). "Six months after ART initiation or reinitiation, we observed significant decreases in levels of HIV VL, CRP and ferritin, and increased levels of plasma iron among participants with co-infections." (PMID 38725704, 2024). "We found that prealbumin and CRP still has a distinguishing effect on Omicron and Flu A/B co‐infection compared to the mono‐infection." (PMID 38270315, 2024). "If serum CRP levels increase in the context of viral lower airway infection, the primary reason for this elevation is often the emergence of bacterial co-infection." (PMID 39064460, 2024). "The optimal cut-off values to predict bacterial co-infection according to Youden’s J statistics in the studied cohort are CRP = 220 mg/L (SE = 0.524; SP = 0.806), PCT = 0.8 μg/L (SE = 0.667; SP = 0.944), and IL-6 = 40 ng/L (SE = 0.714; SP = 0.750)." (PMID 38391578, 2024). "The sign of abdominal pain, the co-infection of IBV, and the abnormally high levels of lymphocytes and CRP, came into light as the independent risk factors of pediatric hospitalization due to IAV infection." (PMID 38249383, 2023). "Conversely, the sign of abdominal pain, the IBV co-infection, and the levels of lymphocytes and CRP, put the pediatric patients infected with IAV higher odds for hospitalization." (PMID 38249383, 2023). "It has been reported that patients with bacterial co-infection had significantly higher serum CRP levels than patients with HIN1 infection alone." (PMID 37249974, 2023). "Again, we identified that high neutrophil count (≥9.4 × 109/L), PCT (≥0.2 ng/mL), and CRP (≥108 mg/L) were all independent predictors of co-infection at ICU admission." (PMID 37510807, 2023). "Co-infections usually increase the levels of C-reactive protein (CRP) and procalcitonin (PCT) in the blood." (PMID 37630481, 2023). "Case 2 showed an increase in white blood cells, mainly neutrophils, and case 3 showed a significant increase in C-reactive protein, therefore, 2 cases were considered early co-infection induced TS." (PMID 37026965, 2023). "Herein, we investigated the association of CRP, WBC, procalcitonin and NLR with a detected bacterial co-infection." (PMID 35100984, 2022).
co-infection (continued). "In the present study, we similarly found that SARS-CoV-2 + rhinovirus co-infection, compared to SARS-CoV-2 mono-infection, was associated with lower laboratory biomarkers, specifically lower median ALT, AST, and CRP." (PMID 36612967, 2022). "The AUC values of PCT and CRP for predicting bacterial co-infection were 0.527 (95% CI 0.464–0.589, p = 0.401) and 0.588 (95% CI 0.525–0.652, p = 0.005), respectively." (PMID 35677912, 2022). "For example, the trajectory of C-reactive protein concentration during the first week of hospital admission predicts bacterial co-infection and supports antimicrobial decision-making." (PMID 35644124, 2022). "The AUC value of CRP for predicting bacterial co-infection was 0.588 (95% CI 0.525–0.652, p < 0.001), showing sensitivity and specificity of 0.43 and 0.76, respectively." (PMID 35677912, 2022). "Factors including the ratio of the actual values to the cut-off values of AIGAs, WBC, N, HGB, CD4+T cells, IgG, IgM, IgA, serum globulin, ESR, and CRP were taken as potential risk factors for TM and NTM co-infection." (PMID 34376749, 2021). "High levels of CRP observed from day 2 to day 23 suggested that there should be viral and bacterial coinfection in the patient’s respiratory system." (PMID 33816347, 2021). "HCoV, and in particular Betacoronavirus, detection, was also associated with blood culture positivity, medically significant CRP levels and high pneumococcal densities in the NP/OP samples, all indicators of bacterial co-infection." (PMID 34452378, 2021). "With higher rates of bacterial co-infection confirmed (32%), the receiver operating characteristic (ROC) curve for positive bacterial infection was similar for CRP and PCT (area under the curve of 0.86 and 0.88, respectively)." (PMID 34572701, 2021). "Univariate analysis for risk factors of TM and NTM co-infection found that high level of AIGAs, WBC, N, HGB, IgG, IgM, IgA, serum globulin, ESR, and CRP and low level of CD4+T cells were taken as potential risk factors for TM and NTM co-infection." (PMID 34376749, 2021). "We found that factors including the ratio of the actual values to the cut-off values of AIGAs, WBC, N, HGB, CD4+T cells, IgG, IgM, IgA, serum globulin, ESR, and CRP were taken as potential risk factors for TM and NTM co-infection." (PMID 34376749, 2021). "Elevated procalcitonin levels are reportedly suggestive of bacterial co-infection, and raised C-reactive protein (CRP) occurs with severe infection." (PMID 32621013, 2020). "Using PCT or CRP levels alone, the areas under the curves (AUCs) for predicting bacterial co‐infections were 0.801 (95% CI, 0.772‐0.855) and 0.762 (95% CI, 0.722‐0.803), respectively." (PMID 30443990, 2019). "Significantly higher PCT (1.46 vs 0.21 ng/mL, P < 0.001) and CRP (19.20 vs 5.10 mg/dL, P < 0.001) levels were detected in the bacterial co‐infection group than in the H1N1 infection‐alone group." (PMID 30443990, 2019). "In this study CRP was a useful predictor of bacterial co-infection, which corroborates with previous data." (PMID 31694565, 2019). "A CRP level of 40 mg/L or more had a sensitivity of 85.7% and a specificity of 56.8% to detect a bacterial co-infection." (PMID 31694565, 2019). "The primary aim of this analysis was to determine the influence of HIV co-infection and host factors on serological biomarkers, using anti-A60 IgG and IgA and C-reactive protein as MTB-specific and innate markers of host immunity, respectively." (PMID 30935095, 2019). "Although previous studies have focused on using CRP levels to detect bacterial co‐infections in patients with H1N1 infections, the evidence from these studies is inconsistent." (PMID 30443990, 2019). "Children with co-infection had a longer fever process, higher leukocyte count, higher C-reactive protein compared with single infection (P < 0.05)." (PMID 29970200, 2018).